ENSG00000261884 (novel transcript)
Gene: Protein-coding gene on chromosome 16 (67,929,614 to 67,936,017, reverse strand). Ensembl gene ENSG00000261884.
Genetic constraint (gnomAD): Missense variants: 67 observed, 86.81 expected, observed/expected ratio (o/e) 0.77, 90% interval 0.63 to 0.95. Synonymous variants: 30 observed, 36.24 expected, observed/expected ratio (o/e) 0.83, 90% interval 0.62 to 1.12.